PARP1 (poly(ADP-ribose) polymerase 1)
Diseases named in the same sentence as PARP1 in open-access papers (continued):
Sharing a sentence is not in itself a finding about the gene and the disease.
hepatocellular carcinoma (continued). "We then concluded that PARP-1 played a crucial role in the cell proliferation of hepatoma cells." (PMID 24367566, 2013). "For example, disulfiram–Cu enhances PD-L1 levels in hepatocellular carcinoma (HCC) cells by inhibiting PARP1 and promoting GSK-3β phosphorylation, which reduces T-cell infiltration." (PMID 39867656, 2024). "UHRF2 enhances autophagy and oncogenic traits in hepatocellular carcinoma (HCC) by interacting with PRDX1 and PARP1, suggesting its potential as a biomarker and therapeutic target for HCC." (PMID 39315094, 2024). "For example, in hepatocellular carcinoma (HCC) the lncRNA lncPARP1, which was significantly up-regulated in HCC patients, directly increased the expression of its target PARP1 acting in cis, thus triggering genomic instability and disease progression." (PMID 33808562, 2021). "Moreover, targeting PARP-1 may be a promising therapeutic approach against human hepatocellular carcinoma." (PMID 24367566, 2013). "Beyond PARP1, PARP14 directly promotes aerobic glycolysis (the Warburg effect) in hepatocellular carcinoma by modulating PKM2, linking ADP-ribosylation to pro-tumor glycolytic bias." (PMID 41460301, 2025). "For example, in hepatocellular carcinoma, TLR9 agonist treatment decreased PARylation of STAT3 and expression of PARP-1." (PMID 36077221, 2022). "MicroRNA 223 is up-regulated in the multistep progression of Barrett’s esophagus and modulates sensitivity to chemotherapy by targeting PARP1, it also modulates multidrug resistance via downregulation of ABCB1 in hepatocellular carcinoma cells." (PMID 26055874, 2015). "PRKDC, PARP1, NPM1 and XRCC6 are hepatocellular carcinoma over-expression genes which modulate cell cycle regulation network through the modulation of UBC." (PMID 24564241, 2013). "In hepatocellular carcinoma cells, PARP-1 activation inhibits the SP1 signaling pathway to promote cell proliferation, whereas PARP-1 inhibition enhances SP1-mediated expression of checkpoint proteins (e.g., p21 and p27), leading to cell cycle arrest at the G0/G1 phase." (PMID 41304867, 2025). "Moreover, morin hydrate reversed the acquired resistance of cisplatin-resistant hepatocellular cancer HepG2DR cells by impairing PARP-1/HMGB1-dependent autophagy; indeed, PARP-1 autophagy appears to be regulated by the PARylation of HMGB1." (PMID 34025826, 2021). "Combinations of niclosamide and TRAIL enhanced the sub-G1 population and PARP-1 cleavage, and niclosamide induced up-regulating DR5 and down-regulating c-FLIP in other cancer cells (renal carcinoma; A498 and ACHN, and hepatocellular carcinoma; SK-Hep1)." (PMID 30189637, 2018). "However, there is little research into whether PARP-1 affects the hepatocellular carcinoma (HCC) recurrence after liver transplantation." (PMID 29179487, 2017). "Moreover, both PARP-1+/+ and PARP-1−/− mice developed epithelial tumors of the lung (adenomas, adenocarcinomas) and ofthe liver (hepatocellular carcinomas)." (PMID 19415146, 2008). "Additionally, PARP1 variably modulates autophagy via the MRPL21-PARP1 axis to promote chemoresistance in head and neck squamous cell carcinoma, while being activated by UHRF2 to promote autophagy and malignancy in hepatocellular carcinoma." (PMID 41460301, 2025). "Moreover, miR-223 was demonstrated to rescue the cellular response to anticancer drugs by modulating ABCB1 (ATP-Binding Cassette Sub-Family B Member 1) in hepatocellular carcinoma and targeting PARP1 (poly(ADP-ribose) polymerase 1) in esophageal adenocarcinoma." (PMID 27577078, 2016). "Taken together, these data indicated that PARP-1 inhibition attenuated the poly(ADP-ribosyl)ation of Sp1 and significantly increased the expression of Sp1 target genes, resulting in G0/G1 cell cycle arrest and the decreased proliferative ability of the hepatoma cells." (PMID 24367566, 2013). "Hepatocellular carcinoma (HCC) has been demonstrated to have higher levels of PARP1 and PARP2 expression when compared to matched non-malignant tissue." (PMID 34440228, 2021).
hepatocellular carcinoma (continued). "Evaluation of PARP-1 protein expression in hepatocellular carcinoma (HCC) by western blotting revealed that it was significantly increased in HCC, especially moderately differentiated, compared with the non-tumour samples." (PMID 19568233, 2009).
neuroblastoma (55 papers, 2009 to 2025). Neuroblastoma (NB) is the most common solid, extracranial childhood tumor. "Compared with other solid tumor types, we previously showed that high-risk neuroblastomas have among the highest PARP1 gene expression." (PMID 36396952, 2022). "While PARP1 expression is elevated in high-risk neuroblastoma tumors relative to the majority of normal tissues, the bone marrow compartment shows high PARP1 expression, which causes concern for on-target normal tissue toxicity from [211At]PTT3." (PMID 36396952, 2022). "FOXD3-AS1 expression is reduced in neuroblastomas, thus causing a decreased expression of tumor suppressor genes by a PARP1-dependent mechanism." (PMID 33804735, 2021). "mRNA expression of the PARP family of proteins has been correlated with MYCN amplification prognosis in neuroblastoma and here we provide in vitro evidence that PARP1 protein and PAR activity is increased in association with MYCN expression." (PMID 32577161, 2020). "Although PARP1 expression was recently shown to be associated with poor prognosis in patients with neuroblastoma, we found that high PARP1 expression was associated with high OS and PFS in patients with SCLC." (PMID 33134168, 2020). "We further investigated the effects of three PARP1 SNPs on the neuroblastoma risk after stratified by age, gender, tumor sites, and INSS stages." (PMID 31413734, 2019). "The main limitation was the relatively small sample size, which impairs our capacity to detect weak association between PARP1 gene SNPs and neuroblastoma risk." (PMID 31413734, 2019). "Future studies are needed to validate our findings and target the functional role of PARP1 polymorphisms in neuroblastoma risk." (PMID 31413734, 2019). "In the current study, we comprehensively evaluated the association between the genetic variants in PARP1 gene and neuroblastoma risk." (PMID 31413734, 2019). "Further investigations of the association between PARP1 gene SNPs and neuroblastoma risk are warranted." (PMID 31413734, 2019). "In this multi-center study, we aimed to elucidate the contributing role of PARP1 SNPs in neuroblastoma risk." (PMID 31413734, 2019). "Previous reports have implicated the role of PARP1 in cancer generally and neuroblastoma specifically." (PMID 29298329, 2018). "Abnormalities in the non-homologous end joining repair pathway, such as increased PARP-1 and DNA Ligase protein expression, have been implicated in neuroblastoma cell survival and pathogenicity." (PMID 27515310, 2016). "The expression of FEN1, PARP1, and DNA ligase 3 significantly increases in high-risk neuroblastoma." (PMID 41189817, 2025). "However, Avitabile M showed that the G allele of rs907187 was associated with a better response to induction therapy in neuroblastoma patients, supporting the potential role of PARP1 as a candidate gene for neuroblastoma treatment failure." (PMID 37329186, 2023). "High-risk neuroblastomas exhibit among the highest PARP1 expression across solid tumors." (PMID 36396952, 2022). "Herein, we for the first time investigated whether PARP1 gene SNPs (rs1136410, rs2666428, rs8679) could affect the neuroblastoma susceptibility in Chinese children." (PMID 31413734, 2019). "In all, this study suggests that PARP1 polymorphisms may be weakly associated with neuroblastoma risk." (PMID 31413734, 2019). "Pifithrin-α also significantly inhibited proteolytic activation of apoptotic factors such as caspase-9, caspase-3 and inactivation of PARP-1, providing a strong evidence for a functional association of Bex genes in neuroblastoma cell apoptosis mediated by curcumin." (PMID 28145533, 2017). "Accordingly, both PARP-1 inhibitors may be considered of benefit to high-risk neuroblastoma patients undergoing targeted radiotherapy." (PMID 27515310, 2016).
neuroblastoma (continued). "Indeed, increased PARP-1 expression has previously been associated with greater neuroblastoma cell genomic instability, higher neuroblastoma stage and poor overall survival, suggesting these tumours will be susceptible to PARP-1 inhibition." (PMID 27515310, 2016). "We observed that high PARP1 mRNA level is associated with unfavourable prognosis in 3 public gene expression NB patients’ datasets and in 20 neuroblastomas analysed by qRT‐PCR." (PMID 32103589, 2020). "However, whether common single nucleotide polymorphisms (SNPs) in PARP1 gene are associated with neuroblastoma risk has received relatively few attentions." (PMID 31413734, 2019). "Thus, we performed a multi-center case-control study to explore whether PARP1 gene polymorphisms could predispose to neuroblastoma risk." (PMID 31413734, 2019). "For example, the MZF1 antisense RNA 1(MZF1-AS1)/poly (ADP-ribose) polymerase 1 (PARP1)/E2F1 axis enhances the malignant progression of neuroblastoma by promoting the synthesis of proline." (PMID 41331125, 2025). "The high expression of DNA ligase 3, PARP1, and FEN1 is significantly associated with poor overall survival in neuroblastoma." (PMID 41189817, 2025). "The inhibition of DNA ligase 3 or PARP1 enhances the accumulation of DSBs and promotes apoptotic cell death in neuroblastoma cells." (PMID 41189817, 2025). "A significant alteration in caspase-3 and PARP-1 cleavage was also observed when these compounds were applied to neuroblastoma cells." (PMID 41471783, 2025). "In neuroblastoma, it has been shown to increase mitochondrial dysfunction and endoplasmic reticulum stress by stimulating caspases (caspase-3, 4, 8, 9, 12), PARP1, GRP-78/Bip, GRP-94/gp96, IRE1α, and TRAF2." (PMID 38249515, 2023). "A study using a pancreatic mouse cell line found that the inhibition of PARP-1 reduces CSC features, similar to the results found in neuroblastoma in which PARP-1 promotes stemness." (PMID 36902215, 2023). "High CHK1 mRNA expression is associated with a reduced survival in neuroblastoma patients, independently from MNA, with the same trend we previously reported for PARP1 and PARP2." (PMID 34508175, 2021). "PARP1 interaction with long noncoding RNAs (lncRNAs) seems to play a role in pediatric neuroblastomas." (PMID 33804735, 2021). "We also show that treating the neuroblastoma cell line with these compounds resulted in a significant alteration in caspase-3 and PARP-1 cleavage." (PMID 34451847, 2021). "We also tested the association between PARP1 and PARP2 expression with clinical outcome by quantitative real‐time PCR (RT‐qPCR) analysis of 20 mRNA samples extracted from stage 4 neuroblastomas." (PMID 32103589, 2020). "We successfully genotyped three potentially functional PARP1 SNPs (rs1136410 A>G, rs2666428 T>C, rs8679 A>G) in 469 neuroblastoma cases and 998 controls." (PMID 31413734, 2019). "For example, overexpression of lncRNA FOXD3-AS1 induces neuronal differentiation and decreases the aggressiveness of neuroblastoma cells through interacting with PARP1 and inhibiting the activation of CCCTC-binding factor (CTCF)." (PMID 29776974, 2018). "In a neuroblastoma cell line, PARP-1 has an important role in the molecular mechanism of amyloid beta peptide damage, inducing mitochondrial dysfunction and cell death by a 60% increase in its activity." (PMID 29472838, 2018). "We found that miR-193b significantly increases both caspase-3/7 activity and PARP-1 cleavage in six of nine investigated neuroblastoma cell lines within 24 hours." (PMID 29719597, 2018). "We showed that CRISPR/Cas9n targeting of Plaur gene resulted in inhibition of neuroblastoma proliferation, significant reduction in the number of Ki-67 positive cells, caspase 3 activation and PARP-1 cleavage." (PMID 30034627, 2018). "DNA Ligase III, Ligase I, and PARP1 silencing significantly decreased neuroblastoma markers expression (TH, Phox2b, and TRKB)." (PMID 29238067, 2017).
neuroblastoma (continued). "Here we show for the first time that RNF146 expression is indeed sufficient to prevent PARP1-dependent cell toxicity in neuroblastoma PD model cell lines." (PMID 29290984, 2017). "Replication stress was recently also detected upon olaparib treatment of MYCN-amplified neuroblastoma, which also express high PARP1/2 levels." (PMID 29262611, 2017). "The alternative PARP-1 inhibitor niraparib (formerly MK-4827) effectively sensitised a panel of neuroblastoma cells to external beam radiation." (PMID 27515310, 2016). "In this study, we observed, in pre-clinical models of neuroblastoma, that the third generation PARP-1 inhibitors, rucaparib and olaparib, significantly enhanced the efficacy of ionising radiation, in the form of external beam X-rays or 131I-MIBG." (PMID 27515310, 2016). "The sensitivity of MYCN amplification to poly (ADP-ribose) polymerase 1 (PARP1) inhibition in neuroblastoma and the identification of the MYCN-PARP1/2-DNA damage repair (DDR) pathway as a driver of transition to NEPC provide the rationale for combining AURKA inhibitors with PARP1 inhibitors." (PMID 38398199, 2024). "MMEJ machineries including DNA ligase III (LIG3), DNA ligase I (LIG1), and poly(ADP-ribose polymerase 1) (PARP1) are highly expressed in neural crest stem cells, the cell of origin for neuroblastoma, and thought to contribute to the tumor's ability to survive double-stranded break triggering events." (PMID 37457440, 2023). "Similarly, noncoding RNA activated by DNA damage (NORAD) knockdown in neuroblastoma cells upregulates the poly [ADP-ribose] polymerase 1 (PARP1), a DNA damage sensor for DNA repair." (PMID 36230902, 2022). "Similarly, PARP1/2 was highly expressed in MYCN-amplified neuroblastomas compared with neuroblastomas with MYCN single copy." (PMID 34069817, 2021). "Our findings failed to provide evidence of the conferring role of the PARP1 gene polymorphisms in the risk of neuroblastoma." (PMID 31413734, 2019). "Moreover, ectopic over‐expression of FOXD3‐AS1 impairs the aggressiveness of neuroblastoma cells through interacting with PARP1 to inhibit the poly(ADP‐ribosyl)ation and activation of CTCF, thereby repressing downstream tumor‐suppressive genes expression." (PMID 29923329, 2018). "Our findings suggest that the administration of PARP-1 inhibitors and 131I-MIBG to high risk neuroblastoma patients may be beneficial." (PMID 27515310, 2016). "Our findings suggest that the administration of PARP-1 inhibition and 131I-MIBG to high-risk neuroblastoma patients may be beneficial." (PMID 27515310, 2016). "Finally, rucaparib and olaparib were shown to be equipotent inhibitors of PARP-1 activity and displayed analogous levels of radiosensitisation in neuroblastoma models." (PMID 27515310, 2016). "PARP-1 inhibitors are increasingly being considered for the treatment of neuroblastoma." (PMID 27515310, 2016). "In the present study we focused on the comprehension of the molecular mechanisms that lead to PARP-1 activation by Aβ in SH-SY5Y neuroblastoma derived cells and in transgenic mice TgCRND8, an early onset model of AD and to the downstream ways activated by PARP-1." (PMID 24086258, 2013). "Compared to the control, both treatment protocols showed a marked cleavage of PARP-1 in NB cell line Kelly and IMR-32, indicating effective induction of apoptosis by both RIST and TIST treatment in neuroblastoma cells." (PMID 33390782, 2021). "Furthermore, targeted inhibition of CTSL in a human neuroblastoma cell line blocked activation of caspase-3 and PARP-1, similarly to our observations in human primary macrophages, in which inhibition of CTSL influenced autophagy but was unable to induce apoptosis." (PMID 32927704, 2020). "However, till now, no reports have evaluated the association of PARP1 gene polymorphisms with neuroblastoma risk." (PMID 31413734, 2019).
neuroblastoma (continued). "Focusing on POU5F1 regulation, it has been shown that PARP1 directly binds to the epigenetic factor PHF20 at the promoter region of POU5F1, activating its transcription in neuroblastoma cells." (PMID 40986050, 2025). "The results from the protein expression analysis revealed that, during the treatment of the neuroblastoma cell line SH-SY5Y with the tested compounds, apoptotic proteins such as Bax, cleaved caspase-3, and cleaved PARP-1 were upregulated." (PMID 41471783, 2025). "WEE1, CHEK1, BRCA1, FANCD2, PARP1, and phosphorylation of CHEK1 and ATR were significantly reduced in TRPM2 deleted neuroblastoma and myeloid leukemia cells after doxorubicin treatment." (PMID 35428820, 2022). "Interestingly, while miR-193b only slightly increased caspase-3/7 activity in CHLA-15 cells (1.26 fold), it significantly increased PARP-1 cleavage in this cell line within 24 hours post-transfection, indicating that miR-193b may also induce caspase-independent cell death in neuroblastoma." (PMID 29719597, 2018). "Since PARP1 activation has been reported in various neurodegenerative models including PD, we evaluated the therapeutic potential of RNF146 expression in neuroblastoma SH-SY5Y cells challenged with PD-related toxins." (PMID 29290984, 2017). "The higher CHK1 and PARP1 expression in MNA compared to non-MNA neuroblastoma is also recapitulated in the cell lines (F and our previous work), which therefore represent good models to study the effects of combined PARP and CHK1 inhibition." (PMID 34508175, 2021). "We have shown that targeting of the Plaur gene in mouse neuroblastoma Neuro 2A cells by CRISPR/Cas9n results in ~60% decrease in cell proliferation (p<0.05), reduction in the number of Ki-67 positive cells, caspase 3 activation and PARP-1 cleavage." (PMID 30034627, 2018). "In the present study, we determined the radiosensitising potential of rucaparib and olaparib, two PARP-1 inhibitors currently undergoing phase II/III clinical investigation, in combination with external beam X-radiation or the neuroblastoma-targeting radiopharmaceutical 131I-MIBG." (PMID 27515310, 2016). "To determine whether DX2 acts as a competitive inhibitor of AIMP2, suppressing AIMP2-induced PARP-1 activation and neuronal cell death, we transfected neuroblastoma cells with DX2-plasmid vectors and -siRNA, and subsequently measured the binding of AIMP2 to PARP-1." (PMID 38172953, 2024). "In addition, we did not observe cell death induction as assessed by PARP-1 cleavage or Annexin V/PI staining, indicating differential sensitivity of neuroblastoma cell lines, depending on MYCN amplification status." (PMID 34884931, 2021). "Furthermore, our results show that there is no statistically significant positive correlation between PARP-1 expression and PARP-1 activity in the panel overall or when comparing cells from the same tissue of origin, e.g., the five neuroblastoma cell lines." (PMID 19568233, 2009).